LGALS1 (galectin 1)
Diseases named in the same sentence as LGALS1 in open-access papers (continued):
Sharing a sentence is not in itself a finding about the gene and the disease.
benign gynecologic tumors (1 paper, 2015). "galectin-1 in sera was evaluated by ELISA in a pilot panel of EOC patients, healthy volunteers, patients with benign gynecologic tumors or other gynecologic malignancies." (PMID 26589590, 2015).
bone metastasis (1 paper, 2024). Transfer of a neoplasm from its primary site to bones. "Next, we analysed immune cell infiltration in patients with PCa and with or without bone metastasis, finding a positive correlation between CFH, APOC1 and LGALS1 and various immune cell types." (PMID 39098992, 2024).
Burkitt lymphoma (1 paper, 2014). A rare form of malignant mature B-cell non-Hodgkin lymphoma. "The data are consistent with the previous reports showing the interaction between galectin-1 and CD45 in Burkitt’s lymphoma cell line." (PMID 24589677, 2014).
cardiac hypertrophy (1 paper, 2018). "The profile of inflammatory and fibrotic proteins altered in response to cardiac hypertrophy induced by AAC showed a significant increase in the expression of the fibrotic protein, galectin-1, by 2.5 fold of change in comparison to control." (PMID 29426916, 2018).
cardiomyopathy (1 paper, 2023). A disease of the heart muscle or myocardium proper. "More importantly, deletion of Lgals1 did not impact cardiomyopathy and the reduction in fractional shortening caused by Zdhhc3 overexpression." (PMID 37926281, 2023). "However, loss of Rac1 or other identified zDHHC3 targets Gαq/11 or galectin-1 does not diminish zDHHC3-induced cardiomyopathy, suggesting multiple effectors and pathways promoting decompensation with sustained zDHHC3 activity." (PMID 37926281, 2023).
cervical intraepithelial neoplasia (1 paper, 2025). "Compared with the normal cervical lesion tissue, the levels of PIBF and Galectin-1 in the precervical lesion tissue were significantly increased, suggesting that their elevated levels are significantly associated with the progression of cervical intraepithelial neoplasia." (PMID 41210885, 2025). "This study aimed to discuss the significance of PIBF and Galectin-1 in cervical dysplasia tissue." (PMID 41210885, 2025).
cervical tumor (1 paper, 2017). "It is likely that abundantly secreted galectin-1 proteins in stroma surrounding cervical tumors promoted tumor cell migration, invasion, and metastasis." (PMID 28842515, 2017).
chondroblastic osteosarcoma (1 paper, 2021). An osteosarcoma characterized by the presence of atypical cartilage of variable cellularity. "The differentiation between chondroblastic osteosarcoma and conventional CHS was also found to be possible using galectin-1 (GAL-1), expressed by normal murine osteoblast and involved in cell growth differentiation, adhesion, migration, and apoptosis." (PMID 34069269, 2021).
chondrosarcoma (1 paper, 2025). A malignant cartilaginous matrix-producing mesenchymal neoplasm arising from the bone and soft tissue. "Galectin-1 serves as a diagnostic marker distinguishing chondroblastic OS from conventional chondrosarcoma, and has also been linked to OS progression and metastasis." (PMID 40895569, 2025).
chorioretinal diseases (1 paper, 2023). "In the eye, an increase in galectin-1 is associated with various chorioretinal diseases, in which retinal pigment epithelium (RPE) cells play a crucial role in disease development and progression." (PMID 37628816, 2023). "In summary, all these studies indicate that galectin-1 could play a critical role in proliferative chorioretinal diseases." (PMID 37628816, 2023).
Cirrhosis (1 paper, 2023). A chronic disorder of the liver in which liver tissue becomes scarred and is partially replaced by regenerative nodules and fibrotic tissue resulting in loss of liver function. "We examined the Oncomine database and determined that Galectin-1 expression in liver tissues was significantly higher in patients with HCC or cirrhosis than in those without HCC or cirrhosis." (PMID 37433225, 2023).
co-infection (1 paper, 2021). "The co-infection with TVV+TV and P. bivia synergistically upregulated galectin-1, -9 and IL-1β (p <0.001)." (PMID 34422675, 2021).
diabetic foot ulcers (1 paper, 2022). "Galectin-1 also has a role in the regeneration of peripheral nerves and wound healing, which could be relevant in diabetic peripheral neuropathy and diabetic foot ulcers." (PMID 36295832, 2022).
ductal carcinoma of (1 paper, 2016). "We also explored the data from The Human Protein Atlas for the expression of galectin-1 in ductal carcinomas of women between 27–40 years of age." (PMID 27223428, 2016). "The galectin-1 expression profile in tumor and benign tissue sections of ductal carcinomas was also comparable to VEGF, a multifunctional cytokine, most clinically exploited for vascular targeting in tumors." (PMID 27223428, 2016). "Enlarged images of the ductal carcinoma tissue sections (20×) demonstrated the stromal enrichment of galectin-1." (PMID 27223428, 2016). "Furthermore, this difference in the expression of galectin-1 between normal versus the ductal carcinoma tissues of patients was found to be comparable to the expression of vascular endothelial growth factor (VEGF-A) in the same or similar tissues." (PMID 27223428, 2016). "Here we report an elevated expression of galectin-1 in clinical samples from TNBC patients and data collected from the Human protein atlas on ductal carcinoma in women between the ages of 27–40 years." (PMID 27223428, 2016).
embryonal carcinoma (1 paper, 2015). A non-seminomatous malignant germ cell tumor characterized by the presence of large germ cells with abundant cytoplasm resembling epithelial cells, geographic necrosis, high mitotic activity, and pseudoglandular and pseudopapillary structures formation. "In mouse embryonal carcinoma cells, the Sp1 binding site at −62 to −41 bp of the LGALS1 gene was shown to be critical for its induction by butyrate." (PMID 26413750, 2015).
end-stage renal failure (1 paper, 2023). "High levels of LGALS1 have been correlated with increased proteinuria, decreased renal function, and a higher risk of progression to end-stage renal failure." (PMID 38115247, 2023).
endothelial dysfunction (1 paper, 2025). In vascular diseases, endothelial dysfunction is a systemic pathological state of the endothelium (the inner lining of blood vessels) and can be broadly defined as an imbalance between vasodilating and vasoconstricting substances produced by (or acting on) the endothelium. "In addition, experimental models, including Lgals1 knockout mice, have demonstrated that loss of gal-1 expression results in PE-like features, such as exacerbated inflammation, endothelial dysfunction, and restricted placental and fetal growth." (PMID 40839117, 2025).
esophageal cancer (1 paper, 2022). A primary or metastatic malignant neoplasm involving the esophagus. "Galectin-1 autoantibodies were detected in approximately 10% of patients which was confirmed in a follow up study including more esophageal cancer cases as well as other tumor types." (PMID 36497271, 2022). "Whether circulating levels of galectin-1 protein itself rather than autoantibodies have diagnostic or prognostic value in esophageal cancer still needs to be established." (PMID 36497271, 2022).
Ewing sarcoma (1 paper, 2023). A small round cell tumor that lacks morphologic, immunohistochemical, and electron microscopic evidence of neuroectodermal differentiation. "The expression of galectin-1 was capable to be used to differentiate small-cell osteosarcoma from Ewing sarcoma." (PMID 37964984, 2023).
Fabry disease (1 paper, 2020). Fabry disease (FD) is a progressive, inherited, multisystemic lysosomal storage disease characterized by specific neurological, cutaneous, renal, cardiovascular, cochleo-vestibular and cerebrovascular manifestations. "Moreover, a correlation of MMP2 with MSSI and other signs of cardiomyopathy in Fabry disease were reported (LVH, LGE, diastolic dysfunction).Additionally, elevated levels of galectin-1 supported the significant role of extracellular matrix remodelling in Fabry disease." (PMID 33138098, 2020).
hand osteoarthritis (1 paper, 2024). "We tested the potential of circulating galectin-1, interleukin (IL)-1 beta, IL-6, and tumour necrosis factor alpha (TNF alpha) levels at baseline in individuals with knee pain as biomarkers for development of radiographic knee and/or hand osteoarthritis (OA)." (PMID 38469554, 2024).
HELLP syndrome (1 paper, 2021). A life-threatening condition that can potentially complicate pregnancy. "For the early diagnosis of HELLP syndrome, some studies suggest using novel genetic biomarkers in association with laboratory markers, new potential tools with clinical utility (Galectin-1 and p65/RelA immunoexpression of placental NF-kB)." (PMID 34828527, 2021).
histoplasmosis (1 paper, 2016). A disease caused by the fungus Histoplasma capsulatum. "Here, we describe our discovery of the role of endogenous galectin-1 (Gal-1) in the immune pathophysiology of experimental histoplasmosis." (PMID 27698545, 2016).
kidney cancer (1 paper, 2006). Primary or metastatic malignant neoplasm involving the kidney. "It will thus be very interesting to evaluate whether the same cells might express these proteins in the hamster kidney cancer model by co-immunostaining with galectin-1 and 3 at various stages of tumor development, including very early stages of DES treatment when only galectin-1 is detected." (PMID 16762066, 2006).
kidney stones (1 paper, 2022). "Sex-based comparisons showed that levels of CD63, MCP-1, and podocin plus galectin-1 positive uEVMPs were higher in females with kidney stones compared to males with kidney stones." (PMID 35673574, 2022). "In contrast, levels of uEVMPs positive for VCAM1, podocin plus galectin-1, claudin-1, URAT1, SLC14A2, uromodulin, SCL12A3, V-ATPase, cytokeratin 19, and neprilysin were all lowered in females with kidney stones compared to control females." (PMID 35673574, 2022).
liver steatosis (1 paper, 2025). "If this relationship can be confirmed with a larger cohort, serum galectin-1 levels may be a diagnostic biomarker for hepatic steatosis." (PMID 40002838, 2025). "Mechanistic studies are necessary to investigate the specific pathways through which galectin-1 contributes to liver steatosis and inflammation." (PMID 40002838, 2025). "Moreover, there were notable correlations between serum galectin-1 and markers of liver steatosis, such as the HSI and FLI." (PMID 40002838, 2025).
lymphedema (1 paper, 2015). Excess fluid collection in tissues, causing swelling. "The increase in total cell numbers in lymph nodes from lymphedema animals was most pronounced in galectin-1−/− mice; we observed a 3-fold increase in the total cell numbers in lymph nodes of galectin-1−/− mice compared with wild type mice." (PMID 26216879, 2015). "We also observed an increase in the absolute numbers of T and B cells in the lymph nodes in galectin-1−/− mice compared with control mice, most pronounced in the lymphedema animals." (PMID 26216879, 2015). "In both sham-treated and lymphedema mice, lymph nodes from galectin-1−/− mice had more total cells than those from wild type mice." (PMID 26216879, 2015). "In a murine lymphedema model, galectin-1−/− animals had increased numbers of migratory dendritic cells in draining lymph nodes, specifically dendritic cells with an immunogenic phenotype." (PMID 26216879, 2015). "In addition to regulating iDC migration in vitro, galectin-1 also appears to regulate iDC migration in vivo in a surgical lymphedema model." (PMID 26216879, 2015). "To ask whether galectin-1 regulates iDC migration from tissue across lymphatic endothelium and into draining lymphatics in vivo, we examined migration of dermal iDCs from the tail to regional, tail-draining lymph nodes using a murine surgical lymphedema model." (PMID 26216879, 2015).
lymphoproliferative disorders (1 paper, 2016). "In LCLs and EBV+ post-transplant lymphoproliferative disorders expression of LGALS1 has been reported upregulated." (PMID 26752561, 2016).
macular edema (1 paper, 2017). "In addition, we evaluated galectin-1 protein levels in aqueous humor samples collected from eyes with macular edema due to branch retinal vein occlusion (BRVO) and central retinal vein occlusion (CRVO)." (PMID 29170525, 2017).
macular holes (1 paper, 2015). A hole in the macula of the retina. "To investigate the production of galectin-1 in PDR eyes, we performed ELISA experiments to measure galectin-1 protein levels in vitreous fluids aspirated from PDR and non-diabetic control eyes with idiopathic epiretinal membrane (ERM) and macular hole (MH)." (PMID 26648523, 2015).
malignant mesothelioma (1 paper, 2020). A malignant neoplasm of the pleura or peritoneum, arising from mesothelial cells. "Here we show that Malignant mesothelioma patients have significantly higher level of Galectin-1, Mesothelin, Osteopontin, VEGF, shed SDC-1, MMP-7, HGF, NRG1-β1 and TIMP-1 compared to benign patients." (PMID 32731396, 2020). "Based on ROC curve analyses, Galectin-1, Mesothelin, Osteopontin, NRG1-β1 and shed SDC-1 performed the best diagnostic capacity to distinguish malignant mesothelioma from benign effusions." (PMID 32731396, 2020). "Among these angiogenesis related biomarkers, we demonstrated that Galectin-1, Mesothelin, shed SDC-1 and MMP-7 are biomarkers that discriminated best between malignant mesothelioma and metastatic adenocarcinomas." (PMID 32731396, 2020). "Our data shows that the level of Galectin-1 and mesothelin are significantly higher in MM patients in comparison with metastatic adenocarcinoma patients whereas, shed SDC-1 and MMP-7 levels are significantly decreased in malignant mesothelioma patients." (PMID 32731396, 2020).
mastitis (1 paper, 2024). Inflammation of breast tissue during lactation or postpartum due to an obstructed duct or infection. "The LGALS1 and GC genes were previously associated with confer mechanisms of maternal-conceptus immune tolerance and clinical mastitis resistance in dairy cattle." (PMID 39512801, 2024).
microcytic anemia (1 paper, 2022). Anemia in which the red blood cell volume is decreased. "Additionally, strong positive relation has been detected in comparison of galectin-1 and IL-33 (r = 0.870; p = 0.001), galectin-1 and IL-1 (r = 0.795; p = 0.001) and IL-33 and IL-1 (r = 0.826; p = 0.001) values in serum of CRC patients with diagnosed microcytic anemia." (PMID 35611243, 2022).
mucinous ovarian tumours (1 paper, 2021). "Further, on comparing epithelial ovarian tumour subtypes with Galectin-1 levels, there was no significance found except between the patients with serous epithelial ovarian tumours (45.47±22.12 ng/ml) and mucinous ovarian tumours (14.55±1.32 ng/ml) (p<0.0071)." (PMID 34556165, 2021).
mucositis (1 paper, 2021). Mucositis is inflammation and damage of the mucous membranes lining the mouth and other parts of the gastrointestinal (GI) tract. "In patients with peri-implant mucositis, increasing peri-implant PD and IL-1β levels directly correlated with increased PISF suPAR (p < 0.001) and galectin-1 (p < 0.05) levels." (PMID 34585876, 2021). "In patients with peri-implant mucositis, PISF suPAR (p < 0.001) and galectin-1 (p < 0.001) levels correlated with PISF IL-1β levels." (PMID 34585876, 2021).
multiple sclerosis (1 paper, 2024). A progressive autoimmune disorder affecting the central nervous system resulting in demyelination. "Thus, increased LGALS1 expression was observed in microglia after stimulation with LPS and in a subpopulation of disease-associated microglia in multiple sclerosis." (PMID 38499808, 2024).
muscular dystrophy (1 paper, 2021). Muscular dystrophy (MD) refers to a group of more than 30 genetic diseases characterized by progressive weakness and degeneration of the skeletal muscles that control movement. "Administration of recombinant galectin-1 has recently been shown to improve muscle function in a mouse model of muscular dystrophy." (PMID 33583770, 2021). "Excitingly, administration of recombinant galectin-1 in a genetic mouse model of muscular dystrophy (newborn mdx mice) displays improved muscle function and sarcolemmal integrity, suggesting critical roles of galectin-1 in myogenesis." (PMID 33583770, 2021).
myelofibrosis (1 paper, 2024). A partial or complete replacement of the bone marrow stroma by fibrous tissue. "When we looked for genes which were differentially expressed in the key interacting cell types in myelofibrosis, only two genes were concordantly dysregulated across cell types – S100a6 and Lgals1." (PMID 39383242, 2024). "Together, these data suggested that galectin-1 signaling might play a key pathological role in myelofibrosis progression and warranted further exploration." (PMID 39383242, 2024). "Objective quantification of staining intensity per high power field view showed a significant increase in galectin-1 with progression to myelofibrosis across patient groups (P < 0.001 for myelofibrosis vs. healthy donors and P < 0.001 for myelofibrosis vs. ET and PV)." (PMID 39383242, 2024). "We therefore tested whether the mechanism of galectin-1 increase in myelofibrosis might occur secondary to TNF stimulation." (PMID 39383242, 2024). "The β-galactoside binding protein galectin-1 emerged as one of only two genes differentially expressed in both the MPN clone and the inflamed stroma in myelofibrosis." (PMID 39383242, 2024). "A progressive and highly significant increase in galectin-1 expression was observed with progression of MPN to fibrosis (monotonic trend from controls to PV/ET to myelofibrosis, P < 0.0055), with a 3.4-fold increase in myelofibrosis vs. controls." (PMID 39383242, 2024). "Notably, a significant increase in LGALS1 was observed in patients with myelofibrosis due to either JAK2V617F or mutCALR, confirming that basophils and mast cells are likely to play an important role in the pathobiology of myelofibrosis in patients and contribute to TNF pro-inflammatory pathways." (PMID 39383242, 2024). "Lgals1 was also highly expressed in monocytes, pro-monocytes and GMPs, but neither the abundance of these cell types nor the per cell Lgals1 expression was increased in myelofibrosis, indicating that monocytes and their precursors are not a source of excess galectin-1 production in myelofibrosis." (PMID 39383242, 2024).